AQP5 (aquaporin 5)
Diseases named in the same sentence as AQP5 in open-access papers (continued):
Sharing a sentence is not in itself a finding about the gene and the disease.
colorectal cancer (continued). "Previous studies by our team have found that AQP5 expression is significantly increased in colorectal cancer tissues and 5-FU-resistant colorectal cancer cells, suggesting that AQP5 overexpression plays a certain role in colorectal tumor progression and chemotherapy resistance." (PMID 40760228, 2025). "However, there are few studies on the relationship between AQP5 and chemotherapy resistance in colorectal cancer cells and the related mechanisms." (PMID 40760228, 2025). "Additionally, AQP5 expression is upregulated in colorectal cancer tissues and influences colorectal cancer prognosis by modulating extracellular regulated protein kinase-1/2(ERK1/2) and p38 MAPK signaling pathway." (PMID 40760228, 2025). "Observed the upregulation of AQP5 enhanced phosphorylation of the protein retinoblastoma (Rb) in colorectal cancer, which could be achieved via stimulating the Ras/ERK/Rb signalling cascade." (PMID 38336645, 2024). "In colorectal cancer and colorectal cancer resistant to 5-fluorouracil (a chemotherapy drug), the upregulated Aqp5 mRNA expression was due to low expression of miR-185-3p that targets Aqp5 mRNA." (PMID 36768212, 2023). "AQP1, AQP3, AQP5, and AQP9 are associated with colorectal cancers; among them, it has been indicated that AQP5 promotes the proliferation and metastasis of CRC; moreover, elevated expression of AQP5 in CRC tissue is associated with a poor prognosis of colorectal cancer." (PMID 36114463, 2022). "One study used AQP5 as a novel biomarker to predict poor clinical outcomes in colorectal cancer." (PMID 35619903, 2022). "Furthermore, the expression and secretion of VEGF-A in colorectal cancer cells were downregulated by AQP5 shRNA." (PMID 31623386, 2019). "AQP1, AQP3, AQP5, and AQP9 all have roles associated with colorectal cancer." (PMID 30555637, 2018). "Moreover, AQP1 is widely over-expressed in tumor tissues of brain, lung, prostate, and colon, and AQP3 and AQP5 are also expressed in the colorectal carcinoma." (PMID 22145049, 2011). "The oncogenic properties of AQP5 in lung and colorectal cancer were examined recently." (PMID 19513079, 2009). "However, the relationship between AQP5 and chemotherapy resistance of colorectal cancer cells and the related mechanisms remain unclear." (PMID 40760228, 2025). "Notably, our previous research has demonstrated that miR-185-3p enhances the chemosensitivity of colorectal cancer cells by targeting AQP5, suggesting that AQP5 may serve as a regulatory target of miRNA-based therapeutics." (PMID 40760228, 2025). "Furthermore, miR-185-3p mimic enhanced the chemosensitivity of colorectal cancer cells via an effect on the Aqp5 mRNA, suggesting such a therapeutic approach may be beneficial to treat 5-fluorouracil-resistant colorectal cancers." (PMID 36768212, 2023). "AQP5 might be a novel prognostic biomarker for patients with colorectal cancer." (PMID 23148732, 2012). "AQP5 may be a novel prognostic biomarker for patients with colorectal carcinoma." (PMID 23148732, 2012). "In colorectal cancer progression, AQP1 and AQP5 expression was found to be induced in the early stage of the disease and maintained stability through the late stage of cancer development." (PMID 39941100, 2025). "AQP5 overexpression plasmid transfected significantly increased AQP5 expression in colorectal cancer cell lines, MTT assay showed that AQP5 overexpression promoted the proliferation of colorectal cancer cells." (PMID 40760228, 2025). "For instance, MSC-derived exosomes have been reported to decrease the mRNA levels of Aquaporin-5 and EGFR in colorectal cancer cells, both of which are important signaling molecules regulating tumor proliferation and metastasis." (PMID 38612457, 2024). "In this research project, we evaluated the immunomodulatory effects of MSC-derived exosomes, as well as MSC’s conditioned media, on AQP5 and EGFR gene expression in a highly invasive colorectal cancer cell line “HCT-116”." (PMID 36114463, 2022).
colorectal cancer (continued). "Within this final set, the largest proportion of studies addressed AQP1, followed by AQP5, AQP4, AQP3 and AQP9, for a diverse array of cancer types, including brain, lung, breast and colorectal cancers." (PMID 32679804, 2020). "AQP5 and AQP9 are potential targets to increase the effectiveness of chemotherapeutic drugs among colorectal cancer patients." (PMID 30555637, 2018). "AQP1, AQP3, AQP5, AQP8 and AQP9 play a clinically relevant role in hepatic cancer as they do in colorectal cancer." (PMID 30555637, 2018). "AQP5 is over-expressed in lung, chronic myelogenous leukemia (CML), ovarian, stomach, or colorectal cancers." (PMID 25886458, 2015). "This study aimed to detect the expression of AQP5 and AQP8 in clinical samples of colorectal cancer and analyze the correlations of their expression with the clinicopathological features of colorectal cancer." (PMID 23148732, 2012). "We employed RT-PCR and immunohistochemical methods to detect the expression of AQP5 and AQP8 in clinical samples of colorectal carcinoma and the paraneoplastic normal colonic tissues." (PMID 23148732, 2012). "AQP5 was discovered to be highly elevated in 14 of 45 colorectal cancer tumour samples, moderately elevated in 29 of them, and not detectable at all in two of them." (PMID 38336645, 2024). "In contrast, silencing AQP5 was shown to inhibit EMT in SW480 and HCT29 cells, and some studies have also shown that AQP5 can induce the EMT process to enhance the migration and invasion of colorectal cancer cells." (PMID 32662230, 2020). "However, the expression of AQP5 and AQP8 in colorectal cancer and the clinical significance remain unexplored." (PMID 23148732, 2012). "Immunohistochemical staining detected AQP5 immunoreactivity in the cytoplasm and plasma membrane of colorectal carcinoma cells, but not in the adjacent normal colorectal tissues." (PMID 23148732, 2012). "The clinical significance of AQP5 and AQP8 in colorectal carcinoma remains largely unexplored." (PMID 23148732, 2012).
xerostomia (29 papers, 2015 to 2025). Dryness of the mouth resulting from reduced salivary secretion. "The inflammatory condition in SS salivary gland causes SGEC death and the downregulation of AQP5 expression resulting in hyposalivation and xerostomia." (PMID 37268950, 2023). "AQP5 deficiency has also been implicated in preclinical models of xerostomia, sialadenitis, and Sjogren’s syndrome, and restoration of aquaporin channels in these tissues is associated with increased saliva secretion." (PMID 35145418, 2022). "AQP5 deficiency is associated with xerostomia, and AQP5 knockout mice have defective saliva secretion." (PMID 35145418, 2022). "The increase in AQP5 expression was used as a marker for the reversal of xerostomia caused by the autoimmune sialadenitis associated with Sjögren’s syndrome, using a low-intensity pulsed ultrasound." (PMID 32630469, 2020). "Our previous study suggests that IXD has a promising potential to increase salivation in diabetes-associated xerostomia through increasing intracellular Ca2+ and activating AQP5 channel." (PMID 30558302, 2018). "In the sample from Pittsburgh, the best model showed that higher caries experience is influenced by a combination of older age, use of medications that cause xerostomia and genetic variation in AQP5 SNPs rs3759129 (p = 0.03) and rs10875989 (p = 0.04)." (PMID 26630491, 2015). "Reduced or loss of AQP5 expression and/or altered AQP5 translocation may participate to xerostomia in patients with head and neck cancer treated with ionizing radiation therapy." (PMID 37681902, 2023). "The loss of AQP5 expression could participate in the development of severe xerostomia in patients undergoing radiotherapy." (PMID 32630469, 2020). "We hypothesized that the disruption in the ER folding capacitance impairs the maturation and folding of amylase or aquaporin-5, might be a possible mechanism of aging-associated dry mouth." (PMID 30558302, 2018). "Aquaporin 5 is implicated in OLP patients in several ways such as impaired salivary functioning, xerostomia or dry mouth, diminished repair ability of the mucosal lesion, increased apoptosis, and probable carcinogenesis in this premalignant lesion." (PMID 40100646, 2025). "In the present study, the salivary level and serum level of aquaporin 5 as a biomarker will be measured in the salivary functioning of patients with OLP suffering xerostomia." (PMID 40100646, 2025). "In this study, for the first time, we have investigated the serum and salivary levels of aquaporin 5 (as a salivary gland biomarker) in oral lichen planus patients with xerostomia." (PMID 40100646, 2025). "JUN and MAPK8 can affect the symptoms of xerostomia and xerophthalmia in SS patients by regulating the expression of AQP5." (PMID 38728503, 2024). "This animal study aims to assess the efficacy of electroacupuncture (EA) in preventing xerostomia, salivary gland hypofunction, and inflammation, as well as the decrease in SG’s acini number and Aquaporin 5 (AQP5) induced by 5-fluorouracil (5−FU)." (PMID 37511411, 2023). "Several therapeutic options have therefore been tested to modulate and/or restore the expression of AQP5 to alleviate xerostomia." (PMID 37681902, 2023). "As a water channel protein, any downregulation of AQP5 would worsen the symptoms of xerostomia experienced by the patient." (PMID 37650040, 2023). "In this review, we seek to elucidate the potential of GPCRs, the inositol 1,4,5-trisphosphate receptor (IP3R), store-operated Ca2+ entry (SOCE), and AQP5, which are essential for salivation, as cellular targets in the etiology of xerostomia." (PMID 36982432, 2023). "Reports from the literature and our previous studies revealed the role of AQP5 on the pathophysiology of xerostomia." (PMID 35264956, 2022). "Recently, a study revealed that apigenin alleviates xerostomia via estrogen receptor α-mediated upregulation of aquaporin 5 activation." (PMID 36339416, 2022).
xerostomia (continued). "Immunohistochemistry of submandibular glands revealed the downregulation of AQP5 expression in xerostomia mice compared to control." (PMID 35264956, 2022). "AQP5 is a key protein involved in salivary secretion and its expression downregulates in xerostomia." (PMID 35264956, 2022). "Our results revealed apigenin as a single active component of herbal extract with the potential to treat xerostomia via modulating ERα-AQP5 signaling." (PMID 35264956, 2022). "Effect of low-level laser therapy (LLLT) on the membrane distribution of AQP5 in xerostomia DM patients was also investigated." (PMID 34212290, 2021). "As main transporter protein mediating saliva secretion, AQP5 is recognized as a potential target for the treatment of xerostomia (D’Agostino, C. 2020)." (PMID 34987398, 2021). "Several pathological conditions affecting SG function have been shown to lead to xerostomia and modified AQP5 expression within SG." (PMID 32630469, 2020). "Due to its involvement in the molecular mechanisms of saliva secretion, AQP5 became an additional therapeutic target for the treatment of xerostomia." (PMID 32630469, 2020). "Elevated gene expression of AQP1, AQP4 and AQP5 have been measured in mice models of xerostomia treated with a cell extract from either bone marrow or mesenchymal stem cells, which reduced salivary focus score, and restored saliva and tear flow rates." (PMID 32630469, 2020). "As such, AQP5 represents a potential therapeutic target in different strategies for the treatment of xerostomia." (PMID 32630469, 2020). "The IXD extract highly increased salivary secretion in the submandibular gland by increasing AQP5 and resulted in high amylase expression and represents a potential target to improve xerostomia." (PMID 29614832, 2018). "Altered expression, localization and/or trafficking of AQP5 have been identified in salivary glands following xerostomia of multiple origins." (PMID 26828482, 2016). "Abnormal expression and localization of AQP5 lead to xerostomia in SS." (PMID 39826048, 2025). "The level of Aquaporin 5 in serum and its output in stimulatory, and non‐stimulatory saliva were significantly decreased, the stimulatory and non‐stimulatory saliva flow was reduced, and the degree of xerostomia was significantly higher in the OLP group." (PMID 40100646, 2025). "Shreds of literature, including our own study, indicate that upregulation of AQP5 in SGEC could alleviate xerostomia in SS." (PMID 37268950, 2023). "Moreover, AQP5 expression is downregulated in response to radiation therapy, which can lead to a decrease in salivary flow rates and the development of xerostomia." (PMID 37511411, 2023). "AQP5 are key proteins involved in the pathophysiology of xerostomia." (PMID 35264956, 2022). "Apigenin, or E2 treatment, upregulated AQP5 expression in xerostomia mice." (PMID 35264956, 2022). "Furthermore, apigenin treatment alleviated xerostomia and upregulated AQP5 expression in the submandibular gland in OVX mice." (PMID 35264956, 2022). "In the future, gene editing may be used to treat xerostomia or other SG pathological conditions, for example by increasing AQP5 expression in SG acinar cells or even by simultaneous multigenic gene editing." (PMID 32630469, 2020). "Further studies will be required to assess the effects of these CFTR-targeted drugs on restoration of salivation and on AQP5 protein expression and distribution in SG in patients suffering from other physiopathological conditions leading to xerostomia (e.g., SS patients)." (PMID 32630469, 2020). "Furthermore, in mice SG subjected to radiation, cevimeline prevented both xerostomia and a decrease in AQP5 expression and re-established AQP5 localization to the acinar cell apical membrane." (PMID 32630469, 2020). "Reduced AQP5 protein expression and upregulated, phosphorylated JNK have been observed in submandibular glands of radiation-induced sialadenitis rat model, causing several oral complications (e.g., xerostomia)." (PMID 29614832, 2018).
xerostomia (continued). "Salivary AQP5 has been proposed as a valuable biomarker for diagnosis of dry mouth or xerostomia." (PMID 30555637, 2018). "During senescence, decreased AQP5 expression and/or trafficking might account partly for xerostomia." (PMID 26828482, 2016). "Several therapeutic strategies aiming at relieving xerostomia could arise from the development of drugs targeting AQP5." (PMID 26828482, 2016). "Identification of new drugs capable of increasing AQP5 expression could provide new perspectives for the treatment of xerostomia." (PMID 26828482, 2016). "While AQP5 knock-out mice have no discernable difference in baseline phenotype, changes in AQP5 have been implicated in the pathogenesis of acute lung injury, as well as in the development of xerostomia, lung submucosal glandular secretions, and in the regulation of sweat." (PMID 35145418, 2022). "Therefore, the single active component from plant extract that can modulate estrogen AQP5 signaling in the salivary gland could be a possible drug to rescue xerostomia." (PMID 35264956, 2022). "In addition, future development of drugs enhancing AQP5 activity may offer extra therapeutic leverage to alleviate xerostomia." (PMID 32630469, 2020). "In the treatment of LUTS, muscarinic antagonists contribute to the higher incidence of dry mouth compared with α1A-adrenergic antagonists, which may be correlated with proportionally higher stimulatory effect of mAChR agonists on AQP5 trafficking in parotid gland." (PMID 27367668, 2016). "In murine aging model C57BL/6CrSlc mice characterized by xerostomia, 5-AZA treatment restored salivary gland function, consequently to increased Aqp5 expression resulting from Aqp5 gene promoter methylation." (PMID 36768212, 2023). "Our results demonstrating the effect of Niclosamide on AQP5 abundance and cell volume changes in hypertonic media warrant further investigation of this agent in small animal models of disease, including acute lung injury and xerostomia, where increasing AQP5 abundance could be beneficial." (PMID 35145418, 2022). "Inhibiting HMGB1 reduces SS-induced xerostomia by inhibiting the HMGB1/TLR4/nuclear factor-kappa B (NF-κB) signaling pathway and increasing AQP5 expression." (PMID 35628481, 2022). "In conclusion, our study demonstrates that AQP5 levels are significantly reduced in the serum and saliva of OLP patients, which may contribute to salivary gland dysfunction, xerostomia, and impaired mucosal healing in this condition." (PMID 40100646, 2025). "AQP1, AQP5 and AQP8 have been studied in diabetes-induced xerostomia." (PMID 34212290, 2021). "The effect was also reflected by amylase, aquaporin 5, NHE-1 activities, and its anti-oxidative effect controlling reactive oxygen species, suggesting that the IXD/lactobacillus extract might contribute to dry mouth." (PMID 32392818, 2020).